SPRING1 (SREBF pathway regulator in golgi 1)
Description:
Positively regulates hepatic SREBP signaling pathway by modulating the proper localization of SCAP (SREBP cleavage-activating protein) to the endoplasmic reticulum, thereby controlling the level of functional SCAP.
Synonyms: C12orf49; SPRING; FLJ21415; POST1; LUR1
Tractability: Antibody: UniProt predicts a signal peptide or a membrane-spanning region.
Gene: Protein-coding gene on chromosome 12 (116,710,171 to 116,738,070, reverse strand). Ensembl gene ENSG00000111412.
Subcellular location: Golgi apparatus membrane
Gene Ontology:
Molecular function: protein binding
Biological process: positive regulation of SREBP signaling pathway
Cellular component: Golgi membrane
Genetic constraint (gnomAD): Loss-of-function variants: 14 observed, 25.76 expected, observed/expected ratio (o/e) 0.54, 90% interval 0.36 to 0.85. The upper end of that interval is the gene's LOEUF score, 0.85, which puts it in group 3 of 6, group 1 being the genes least tolerant of losing a copy. Missense variants: 255 observed, 263.86 expected, observed/expected ratio (o/e) 0.97, 90% interval 0.87 to 1.07. Synonymous variants: 93 observed, 101.57 expected, observed/expected ratio (o/e) 0.92, 90% interval 0.77 to 1.09.
Homologues: Orthologues: macaque SPRING1 (100% identical), chimpanzee SPRING1 (99% identical), mouse Spring1 (93% identical), guinea pig SPRING1 (92% identical), tropical clawed frog spring1 (80% identical), rat Spring1 (78% identical), zebrafish spring1 (77% identical), pig SPRING1 (69% identical), Drosophila melanogaster CG15643 (44% identical).
Diseases named in the same sentence as SPRING1 in open-access papers:
SPRING1 is named in the same sentence as 14 diseases in open-access papers, as found by Europe PMC text mining. Sharing a sentence is not in itself a finding about the gene and the disease. The quoted sentences say what the papers report.
colorectal cancer (1 paper, 2023). A primary or metastatic malignant neoplasm that affects the colon or rectum. "In vitro and in vivo studies found that SPRING1 could enhance the growth of colorectal cancer cells, which was related to the increased expression of TMEM41A." (PMID 37478120, 2023). "Studies have shown that the SPRING1 could enhance colorectal cancer cell growth by promoting TMEM41A expression." (PMID 37478120, 2023). "Recent studies have shown the association between transmembrane protein 41A (TMEM41A) and the occurrences and developments of gastrointestinal tumors, with significantly higher expression levels of SREBF pathway regulator in golgi 1 (SPRING1) in colorectal cancer than in adjacent normal tissues." (PMID 37478120, 2023).
SPRING1 also shares sentences with these, for which no sentence is quoted: cancer (2 papers); hepatocellular carcinoma (2); tumor (2); aortic atherosclerosis (1); atherosclerosis (1); cardiovascular disease (1); diphtheria (1); hyperlipidemia (1); Obesity (1); pertussis (1); pneumonitis (1); prostate carcinoma (1); tetanus (1).